ATP11B (ATPase phospholipid transporting 11B (putative))
Description:
Catalytic component of a P4-ATPase flippase complex which catalyzes the hydrolysis of ATP coupled to the transport of aminophospholipids, phosphatidylserines (PS) and phosphatidylethanolamines (PE), from the outer to the inner leaflet of intracellular membranes. May contribute to the maintenance of membrane lipid asymmetry in endosome compartment.
Synonyms: ATPIF; ATPIR; KIAA0956
Tractability: Antibody: its Gene Ontology location is reachable by antibodies, with high confidence; UniProt predicts a signal peptide or a membrane-spanning region. PROTAC: ubiquitination databases record sites on it; its protein half-life has been measured.
Gene: Protein-coding gene on chromosome 3 (182,793,472 to 182,923,011, forward strand). Ensembl gene ENSG00000058063.
Subcellular location: Recycling endosome membrane; Early endosome; Endoplasmic reticulum; Golgi apparatus, trans-Golgi network
Subcellular location (Human Protein Atlas): Centriolar satellite; Cytosol
Pathways (Reactome):
Immune System: Neutrophil degranulation
Transport of small molecules: Ion transport by P-type ATPases
Gene Ontology:
Molecular function: ATPase-coupled intramembrane lipid transporter activity; phosphatidylserine floppase activity; protein binding; monoatomic ion transmembrane transporter activity; ATP binding; ATP hydrolysis activity; magnesium ion binding; nucleotide binding
Biological process: aminophospholipid transport; monoatomic ion transmembrane transport; monoatomic ion transport; phospholipid translocation; phospholipid transport
Cellular component: early endosome; early endosome membrane; endoplasmic reticulum; membrane; phospholipid-translocating ATPase complex; recycling endosome; recycling endosome membrane; azurophil granule membrane; nuclear inner membrane; plasma membrane; endomembrane system; Golgi apparatus
Genetic constraint (gnomAD): Loss-of-function variants: 32 observed, 82.31 expected, observed/expected ratio (o/e) 0.39, 90% interval 0.29 to 0.52. The upper end of that interval is the gene's LOEUF score, 0.52, which puts it in group 2 of 6, group 1 being the genes least tolerant of losing a copy. Missense variants: 774 observed, 951.43 expected, observed/expected ratio (o/e) 0.81, 90% interval 0.77 to 0.86. Synonymous variants: 313 observed, 331.43 expected, observed/expected ratio (o/e) 0.94, 90% interval 0.86 to 1.04.
Homologues: Orthologues: chimpanzee ATP11B (99% identical), macaque ATP11B (99% identical), dog ATP11B (96% identical), rabbit ATP11B (95% identical), mouse Atp11b (93% identical), pig ATP11B (93% identical), rat Atp11b (93% identical), guinea pig ATP11B (92% identical), tropical clawed frog atp11b (78% identical), zebrafish atp11b (60% identical), Drosophila melanogaster CG31729 (25% identical), Caenorhabditis elegans tat-5 (24% identical), and 1 more. Paralogues in human: ATP11A (55% identical), ATP11C (53% identical), ATP8A2 (34% identical), ATP10A (33% identical), ATP8A1 (33% identical), ATP8B1 (33% identical), ATP8B2 (33% identical), ATP10D (33% identical), ATP10B (33% identical), ATP8B4 (33% identical), ATP8B3 (28% identical), ATP9B (27% identical), and 1 more.
Diseases named in the same sentence as ATP11B in open-access papers:
ATP11B is named in the same sentence as 27 diseases in open-access papers, as found by Europe PMC text mining. Sharing a sentence is not in itself a finding about the gene and the disease. The quoted sentences say what the papers report.
ovarian carcinoma (5 papers, 2014 to 2024). A malignant neoplasm originating from the surface ovarian epithelium. "For example, the altered expression of gene ATP11B (encoding ATPase, class VI, type 11B) is associated with cisplatin resistance in ovarian cancer." (PMID 25348067, 2014). "High expression of ATP11B correlates with high-grade tumors in human ovarian cancer samples and with cisplatin resistance in ovarian cancer cell lines, for which sensitivity can be restored by silencing ATP11B." (PMID 38382846, 2024). "ATP11B gene silencing restored the sensitivity of ovarian cancer cell lines to cisplatin, as well as in mice bearing ovarian tumors derived from cisplatin-sensitive and resistant cells." (PMID 37686603, 2023). "In contrast, another study reported that when relative gene expression in a set of primary epithelial ovarian cancer and control ovarian tissues were compared with clinical data and survival of patients, levels of ATP11B were decreased in carcinomas." (PMID 37686603, 2023). "For ovarian cancer, ATP11B high expression was found to correlate with higher tumor grade in human ovarian carcinoma samples and with cisplatin resistance in human ovarian cancer cell lines." (PMID 37686603, 2023). "In contrast, another study reported that levels of ATP11B were decreased in ovarian cancer tissues, suggesting that cisplatin therapy may select for the cells expressing higher levels of ATP11B from a population of low-expressing cancer cells." (PMID 38382846, 2024). "Moreover, ATP11B enhanced cisplatin efflux and ATP11B silencing restored sensitivity of ovarian cancer cells to cisplatin." (PMID 25268716, 2014). "Particularly, siRNA-mediated knockdown of seven genes, CASC10, ATP11B, EMP1, GAS1, SLC6A15, GALNT13, and PDLIM3, significantly reduced cell proliferation of ovarian cancer cells." (PMID 35887085, 2022).
breast carcinoma (3 papers, 2022 to 2025). "Further analysis revealed that cells with low ATP11B expression and high PTDSS2 expression (ATP11BloPTDSS2hi cells) were associated with poor prognosis and enhanced metastasis in breast cancer patients in general." (PMID 35025764, 2022). "Consistently, analyzing the Gene Expression Omnibus (GEO) data set GSE61304 revealed that breast cancer patients with low levels of ATP11B had worse survival outcomes after diagnosis." (PMID 35025764, 2022). "This study demonstrated that low expression of ATP11B, a PS flippase, in conjunction with high expression of PS synthase induced by the Brca1 deletion, caused exposure of PS on the outer leaflet of nonapoptotic breast cancer cells." (PMID 38382846, 2024). "In addition, ATP11B was recently identified as an inhibitor of breast cancer metastasis." (PMID 38382846, 2024). "In our efforts to identify drugs that might inhibit BRCA1-deficient tumor growth and metastasis, we found that paclitaxel or docetaxel treatment can reverse the expression pattern of ATP11B and PTDSS2 in breast cancers and significantly inhibit cancer metastasis." (PMID 35025764, 2022). "Therefore, we searched various databases to identify whether any drugs can have effects on the expression of ATP11B and PTDSS2 during the treatment of patients with breast cancer." (PMID 35025764, 2022). "Our study demonstrates that low levels of ATP11B expression and high levels of PTDSS2 expression promote breast cancer metastasis by increasing nonapoptotic PS populations on the outer leaflet of the cell membrane." (PMID 35025764, 2022).
pancreatic cancer (3 papers, 2022 to 2024). "Since PD-L1 largely determines the efficacy and effectiveness of cancer immunotherapies, the development of ATP11B-targeting drugs is highly promising for anti-pancreatic cancer immunity." (PMID 38382846, 2024). "More importantly, in pancreatic cancer, oncolytic peptide LTX-315 promotes anti-pancreatic cancer immunity by targeting the ATP11B-PD-L1 axis which is dependent of CMTM6-mediated lysosomal degradation." (PMID 37726578, 2023). "Tissue microarray analysis of the 156 pancreatic cancer samples further revealed that ATP11B and PD-L1 were indeed positively correlated." (PMID 35288467, 2022). "The potential clinical significance of the ATP11B-CMTM6 complex in pancreatic cancer evaluated by TCGA data sets revealed that ATP11B was significantly correlated with tumor stage and pathologic grade, while CMTM6 was associated with the pathologic grade." (PMID 35288467, 2022). "Next, ATP11B knockout (KO) and knockdown (KD) pancreatic cancer cell lines, or cell lines overexpressing ATP11B, were generated to evaluate the regulatory relationship between ATP11B and PD-L1 in pancreatic cancer." (PMID 35288467, 2022). "Collectively, these findings revealed the critical role of ATP11B in the immune resistance of pancreatic cancer, indicating the targeting potential of ATP11B in pancreatic cancer immunotherapy." (PMID 35288467, 2022). "The potential impact of targeting ATP11B on the basic characteristics of tumor growth was evaluated in vitro to explore the effect of this potential therapy against pancreatic cancer." (PMID 35288467, 2022). "As demonstrated by IHC staining, significantly reduced PD-L1 expression was also observed in tumor cells after ATP11B depletion, suggesting the strong immune-regulatory function of ATP11B in pancreatic cancer." (PMID 35288467, 2022). "Elevated ATP11B levels correlate with poor outcomes in pancreatic cancer and several other cancers." (PMID 38382846, 2024). "Collectively, these findings demonstrated that ATP11B maintained PD-L1 expression through the prevention of its lysosomal degradation mediated by CMTM6, suggesting that the aberrantly expressed ATP11B might be a potential target to combat pancreatic cancer." (PMID 35288467, 2022). "Taken together, these results suggested that CMTM6 might be involved in the ATP11B action on PD-L1 in pancreatic cancer." (PMID 35288467, 2022). "The current study revealed that LTX-315 targeted ATP11B, a type 4 P-type ATPase (P4-ATPase) localized in the early/recycling endosomes, which was a critical regulator in the maintenance of PD-L1 expression in pancreatic cancer." (PMID 35288467, 2022). "These last findings indicated that ATP11B regulated PD-L1 expression in pancreatic cancer." (PMID 35288467, 2022). "ATP11B was identified as a potential target of LTX-315 and a novel regulator in maintaining the expression of PD-L1 in pancreatic cancer." (PMID 35288467, 2022). "ATP11B was identified as a potential target of LTX-315 and a critical regulator in maintaining PD-L1 expression in pancreatic cancer cells." (PMID 35288467, 2022). "The significant correlation among ATP11B, CMTM6, and PD-L1 was confirmed in clinical samples of pancreatic cancer." (PMID 35288467, 2022). "ATP11B was identified as a potential target of LTX-315, an oncolytic peptide deriving from bovine lactoferrin, and a critical regulator in maintaining Programmed cell Death Ligand 1 (PD-L1) cell surface expression in pancreatic cancer cells." (PMID 38382846, 2024). "No significant stimulation or inhibitory effect was observed on cell colony formation and proliferation in pancreatic cancer cell lines neither with the overexpression of ATP11B nor with its depletion." (PMID 35288467, 2022).
Hypertension (2 papers, 2022 to 2023). The presence of chronic increased pressure in the systemic arterial system. "This EC dysfunction has now been associated with gene ATP11B and subsequent development of the ATP11B knockout rat showed the same cellular, histopathological and cognitive-behavioural abnormalities as the SHRSP, in the absence of hypertension." (PMID 37941765, 2023). "Our strategy of selecting Atp11b, in which there is a mutation in the SHRSP (a rat with SVD pathology) but which is not found in the SHR (a rat with hypertension but lacking overt SVD pathology) led to our prediction that the Atp11bKO rat would be normotensive." (PMID 35635573, 2022). "This combined evidence led to our hypotheses that 1) ATP11B loss or modulation causes EC dysfunction and leads to changes reminiscent of SVD and 2) hypertension is not required for SVD pathology." (PMID 35635573, 2022). "Next, we investigated whether, without hypertension and without ATP11B, there were still signs of EC dysfunction at a juvenile age (3–6 weeks) and an adult age (24–30 weeks)." (PMID 35635573, 2022). "Here, we generated a novel normotensive transgenic rat model, where Atp11b is deleted, and show pathological, imaging and behavioural changes typical of those in human SVD, but that occur without hypertension." (PMID 35635573, 2022).
lung adenocarcinoma (2 papers, 2022 to 2025). A carcinoma that arises from the lung and is characterized by the presence of malignant glandular epithelial cells. "In addition, ATP11B is significantly upregulated in PDAC and lung squamous cell carcinoma and its high expression is associated with a lower survival rate in patients with adrenocortical carcinoma, acute myeloid leukemia, brain lower grade glioma, lung adenocarcinoma, and PDAC." (PMID 35288467, 2022).
brain inflammation (1 paper, 2022). "Considering these data, we are led to assume that the deletion of Atp11b would alter dominant bacterial species in the gut, accelerating aging by aggravating brain inflammation." (PMID 35741595, 2022).
Cognitive impairment (1 paper, 2025). Abnormal cognition is characterized by deficits in thinking, reasoning, or remembering. "It remains to be investigated whether ATP11B exerts its therapeutic effects on pathological LDs primarily through signaling pathways associated with ApoE4 and TREM2, ultimately improving cognitive impairment and AD pathology in AD mice." (PMID 40123832, 2025).
glioblastoma (1 paper, 2024). The most malignant astrocytic tumor (WHO grade IV). "LINC00606 regulates glioblastoma progression by sponging miR-486-3p and interacting with ATP11B." (PMID 38725030, 2024).
glioma (1 paper, 2024). A benign or malignant brain and spinal cord tumor that arises from glial cells (astrocytes, oligodendrocytes, ependymal cells). "Therefore, understanding the underlying mechanisms of LINC00606 and/or ATP11B in glioma has novel implications in future therapies to inhibit glioma progression and recurrence." (PMID 38725030, 2024). "To further explore the role of ATP11B in the proliferation and migration of glioma cells, we knocked down ATP11B or overexpressed ATP11B in U251 and U118 cells." (PMID 38725030, 2024). "As expected, the interaction between LINC00606 and ATP11B is involved in the control of the biological behavior of glioma cells and participates in the regulation of the PI3K/AKT signaling pathway to modulate the apoptosis rate." (PMID 38725030, 2024). "We elucidated the interaction between LINC00606 and ATP11B and the mechanism by which ATP11B, as an interacting protein, inhibits glioma cell proliferation, migration, and colony formation and increases the rate of apoptosis." (PMID 38725030, 2024). "The expression of LINC00606 and ATP11B in glioma and normal brain tissues was evaluated by qPCR, and the biological functions of the LINC00606/miR-486-3p/TCF12/ATP11B axis in GBM were verified through a series of in vitro and in vivo experiments." (PMID 38725030, 2024). "Next, to explore the effect of ATP11B in vivo, U251 cells overexpressing ATP11B (OE ATP11B) was intracranially injected into nude mice in order to construct an in vivo model of glioma." (PMID 38725030, 2024). "On the other hand, it can also regulate the PI3K/AKT signaling pathway to mediate glioma cell proliferation, migration and apoptosis by binding to ATP11B protein." (PMID 38725030, 2024). "Analysis of the 200 clinical samples demonstrates that the mRNA expression level of ATP11B in glioma tissues was significantly reduced in comparison with that in normal brain tissues." (PMID 38725030, 2024). "In conclusion, our findings provide important clues for further study of the molecular mechanism of LINC00606 and ATP11B in glioma." (PMID 38725030, 2024). "In addition, flow cytometry and TUNEL assays show that overexpression of ATP11B significantly increased the apoptosis of glioma cells." (PMID 38725030, 2024). "ATP11B can affect the proliferation, migration, and colony formation of glioma cells." (PMID 38725030, 2024). "ATP11B has been shown to be closely associated with tumor metastasis; however, its role in glioma has not yet been elucidated." (PMID 38725030, 2024). "Additional inquiry unveiled that LINC00606 binding to ATP11B interrupts PI3K/AKT signal transduction and reduces glioma cell apoptosis." (PMID 38725030, 2024). "Moreover, LINC00606 binds to ATP11B and participates in the regulation of the PI3K/AKT signaling pathway, which decreases the level of apoptosis and thus promotes the progression of glioma." (PMID 38725030, 2024). "Furthermore, the expression of 18F-FET in the brains of mice injected with ATP11B-overexpressing U251 cells was significantly reduced as compared with the vector, and OE ATP11B and sh-LINC00606 inhibited the growth of glioma cells in vivo model." (PMID 38725030, 2024). "KEGG enrichment analysis yielded very similar results to those of miR-486-3p target genes, which were mainly enriched in cancer and PI3K/AKT signaling pathways, suggesting that ATP11B may modulate the PI3K/AKT signaling pathway to affect the occurrence and development of glioma." (PMID 38725030, 2024).
malignant glioma (1 paper, 2024). A grade III or grade IV glioma arising from the central nervous system. "It demonstrates that the expression of ATP11B in the human malignant glioma cell lines, U251, U87, and U118, is significantly decreased at both the mRNA and protein levels in comparison with that in the normal human glial cell line HEB." (PMID 38725030, 2024).
Sepsis (1 paper, 2025). Sepsis is defined as life-threatening organ dysfunction caused by a dysregulated host response to infection. "Collectively, our bioinformatic and experimental findings indicate that ATP11B, RBBP7, DOCK10, and NUP160 are implicated in the pathogenesis and progression of sepsis." (PMID 41394771, 2025). "The mRNA expression of ATP11B was upregulated and that of RBBP7 was downregulated in LPS‐induced sepsis, in line with our bioinformatic analysis results." (PMID 41394771, 2025). "Our research shows that ATP11B and RBBP7 emerge as validated, promising biomarkers for sepsis, supported by consistent upregulation/downregulation in both bioinformatics and experimental models." (PMID 41394771, 2025). "Based on our bioinformatic and experimental findings, we further explored the therapeutic potential of ATP11B and RBBP7 within sepsis pathophysiology." (PMID 41394771, 2025). "The mRNA expression of ATP11B was increased, but RBBP7 was downregulated in LPS‐induced sepsis, aligning with the findings from the bioinformatic study." (PMID 41394771, 2025). "This work demonstrated that mRNA expressions of ATP11B were significantly elevated and those of RBBP7 were significantly decreased in LPS‐induced sepsis, aligning with the findings of bioinformatic analysis." (PMID 41394771, 2025). "ATP11B, RBBP7, DOCK10, and NUP160 may play the major role in the occurrence and progression of sepsis." (PMID 41394771, 2025). "ATP11B, upregulated in sepsis, shows a negative correlation with memory B cells and a positive correlation with resting NK cells and activated memory CD4+ T cells, suggesting its role in regulating the transition from hyperinflammation to immunosuppression." (PMID 41394771, 2025).